CFTR (CF transmembrane conductance regulator)
Diseases named in the same sentence as CFTR in open-access papers (continued):
Sharing a sentence is not in itself a finding about the gene and the disease.
cystic fibrosis (continued). "Although HSP90 seems to function predominantly by stabilizing proteins, in cystic fibrosis Ahsa1 downregulation enhances CFTR activity." (PMID 23720234, 2013). "One striking example is the rescue of the most common mutant protein leading to Cystic Fibrosis, the deltaF508 cystic fibrosis transmembrane conductance regulator (CFTR) by the corrector VX-809." (PMID 23460825, 2013). "In Cystic Fibrosis, mutations of the CFTR gene result in defective Cl− secretion and Na+ hyperabsorption by epithelia which leads to airway lumen dehydration and mucus plugging and favours chronic bacterial colonization, persistent inflammation and progressive lung destruction." (PMID 24688726, 2013). "The present report not only provides new understanding of the mechanism involved in CFTR trafficking, but also suggests new approaches in the therapeutic strategies for cystic fibrosis." (PMID 23785472, 2013). "Cystic fibrosis is a simple, Mendelian disorder with complex clinical manifestations that are consequences of CFTR genotype, environmental factors, and heterogeneity throughout the entire genome." (PMID 23630497, 2013). "Cystic Fibrosis is a clinically complex disease caused primarily by mutations in the cystic fibrosis transmembrane conductance regulator (CFTR) gene, which encodes a chloride (Cl-) channel that plays a fundamental role in ion and fluid transport across epithelial surfaces." (PMID 23537407, 2013). "The deleterious activity of HSP90 in cystic fibrosis is thought to be due to HSP90 sequestration of a hypomorphic CFTR." (PMID 23720234, 2013). "In agreement, treatment of a cystic fibrosis mouse model with LPC was shown to increase LV gene transfer of the cystic fibrosis transmembrane conductance regulator (CFTR) gene and improve lung function." (PMID 24236116, 2013). "This tool is crucial for preclinical studies of new drugs for cystic fibrosis treatment, particularly given the difficulties involved in interpreting the effects of treatment due to the potential residual activity of F508del-CFTR." (PMID 23505426, 2013). "The association of TGFβ1 codon 10 CC genotype and the TT genotype of −509 with more severe lung disease in delta F 508 homozygous cystic fibrosis patients was shown by Drumm and coworkers in a large trial involving 808 CFTR F508 del homozygous patients." (PMID 24062613, 2013). "In particular, for molecular genetic testing, it offers specific EQA schemes for 4 diseases: Cystic Fibrosis (CFTR gene), Beta Thalassemia (HBB gene) (BT), Fragile X-Syndrome (FMR1 gene) (FX), and Familial Adenomatous Polyposis Coli (APC gene) (APC)." (PMID 23484150, 2013). "It is well known that the disease progression in cystic fibrosis patients may be diverse in subjects with identical mutation in CFTR gene." (PMID 23343370, 2013). "The number of TG repeats immediately adjacent to 5T is not only significantly associated with the level of alternative splicing of exon 9 of the CFTR gene, but also influences clinical penetrance both in the context of cystic fibrosis and CAVD." (PMID 23820649, 2013). "We are now investigating the potential to purify CFTR-expressing cells and are developing methods to achieve significant pulmonary engraftment of hAECs in animal models of cystic fibrosis." (PMID 23029546, 2012). "Here we report the ability to induce hAECs to express functional CFTR in vitro, providing a valuable tool for a potential cellular therapy for cystic fibrosis." (PMID 23029546, 2012). "Cystic fibrosis (CF; OMIM#219700) is an autosomal recessive disorder due to mutations in the CFTR (Cystic Fibrosis Transmembrane conductance Regulator) gene, which was cloned in 1989." (PMID 22380742, 2012). "Most patients with Cystic Fibrosis carry at least one allele with the F508del mutation, resulting in a CFTR chloride channel protein with a processing, gating and stability defect, but with substantial residual activity when correctly sorted to the apical membranes of epithelial cells." (PMID 23284872, 2012).
cystic fibrosis (continued). "CFTR expression and function is essential for normal respiratory airway function and is defective in individuals with cystic fibrosis." (PMID 23029546, 2012). "Cystic fibrosis clinically impacts multiple organ systems, such that treatment of the basic defect in CFTR is the best way to address the widespread morbidities." (PMID 22973227, 2012). "Patients currently receive therapeutics primarily aimed at treating symptoms of Cystic Fibrosis (CF; Ashlock and Olson, 2011; Cuthbert, 2011), although the first mechanism-based therapy for CF patients harboring a CFTR gating mutation like G551D was recently approved." (PMID 22822398, 2012). "Although the clinical relevance of the Yor1-ΔF gene interaction network for cystic fibrosis remains to be defined, the model appears to be informative with respect to human cell models of CFTR-ΔF." (PMID 23270647, 2012). "Mutations in the gene encoding CFTR may cause cystic fibrosis, a common autosomal recessive disease affecting 1/2,000-4,000 newborns in the Caucasian populations." (PMID 23554779, 2012). "To gain insight into the molecular processes involved in the stability and trafficking of F508del-CFTR we analyzed the common genes following ouabain and low temperature treatments using the GeneGo Cystic Fibrosis platform (MetaCoreTM by GeneGo, Inc.)." (PMID 23060796, 2012). "We now address how the Phe508 deletion in the NBD1 domain of the cystic fibrosis transmembrane conductance regulator (CFTR) protein responsible for cystic fibrosis impacts the binding of CFTR with cellular chaperones." (PMID 22701530, 2012). "In the past decade much has been learned about how Cystic Fibrosis Transmembrane Conductance Regulator (CFTR) folds and misfolds as the etiologic cause of cystic fibrosis." (PMID 23248597, 2012). "Cystic fibrosis occurs when CFTR anion channels, which are especially important in the functioning of ion transporting epithelia, are missing or defective." (PMID 21935358, 2011). "CF is caused by mutations of the CFTR (cystic fibrosis transmembrane conductance regulator) gene." (PMID 21304986, 2011). "Mice homozygous for the disrupted CFTR gene (cftrm1UNC) display many features of cystic fibrosis patients such as meconium ileus, alterations of mucous and serous glands and obstruction of glandular ducts by inspissated material." (PMID 22133269, 2011). "The most common mutation ∆F508 of another ABC transporter of the C subfamily, CFTR/ABCC7, leading to cystic fibrosis, results in CFTR misfolding and retention in the ER, and can raise stress and activate UPR." (PMID 21214890, 2011). "Cystic fibrosis is an autosomal recessive disease that may be caused by more than 1000 different mutations in the cystic fibrosis transmembrane conductance regulator (CFTR) gene." (PMID 22194755, 2011). "Cystic fibrosis is an autosomal recessive disorder caused by mutations in the CFTR gene." (PMID 22125624, 2011). "CF is caused by mutations in the cystic fibrosis transmembrane conductance regulator (CFTR)." (PMID 22174830, 2011). "The identification of strategies to improve mutant CFTR function remains a key priority in the development of new treatments for cystic fibrosis." (PMID 21909392, 2011). "Using the ΔF508 mouse model of cystic fibrosis, we found that the CFTR channel mediates Cl− reabsorption by salivary gland ducts but fluid secretion was normal." (PMID 21304986, 2011). "The pathophysiological events in CF are caused by mutations in the chloride channel protein, cystic fibrosis transmembrane conductance regulator (CFTR), leading to defective trans-epithelial ion transport, airway surface liquid depletion, decreased mucociliary clearance and mucus obstruction." (PMID 22014187, 2011). "Despite the many therapies in the pipeline targeting specific defects in CFTR transcription and expression or modulation of the channel functions, there is still a clinical need for gene therapy-based treatment for cystic fibrosis." (PMID 22046351, 2011).
cystic fibrosis (continued). "Cystic fibrosis is a multisystem, genetic disease caused by mutations in the gene encoding CFTR, which leads to decreased chloride secretion and increased sodium absorption, with resulting decreases in lumenal liquid, in airways, the pancreas, and other organs lined by epithelial cells." (PMID 22203854, 2011). "Cystic fibrosis is the most common life-shortening autosomal recessive disease within the Caucasian population and is caused by mutations in the Cystic Fibrosis Transmembrane Conductance Regulator (CFTR) gene." (PMID 22059807, 2011). "Using the ΔF508 mouse cystic fibrosis model, we previously found that the CFTR channel mediates Cl− reabsorption by salivary gland ducts." (PMID 21304986, 2011). "Several studies have shown the possibility of rescue of membrane targeting of misfolded cystic fibrosis ABCC7/CFTR mutant (ΔF508) by treating either cultured cells or human patients with 4-PBA." (PMID 21935449, 2011). "However, a previous study in IBD patients suggested that heterozygous carriers of the ΔF508 mutation in the CFTR gene, the main susceptibility gene for patients with cystic fibrosis, might exert a protective effect in CD, suggesting opposing effects of genetic risk loci for cystic fibrosis and IBD." (PMID 21559399, 2011). "For instance the cystic fibrosis has large racial disparities and as expected we found large differences in the CFTR gene (rs213950) among different racial groups in our population." (PMID 20565774, 2010). "We found that VCP inactivation prevents neurodegeneration in Rh1P37H flies and VCP inhibition is also sufficient to rescue mutant CFTR from degradation and to partially restore CFTR function in a cellular model of cystic fibrosis." (PMID 20865169, 2010). "Cystic Fibrosis is the most common life-shortening autosomal recessive disorder in Caucasian populations and its clinical symptoms are the consequence of mutations in the CF transmembrane conductance regulator (CFTR) gene on chromosome 7." (PMID 21994695, 2010). "CF is an autosomal recessive inherited disorder characterised by mutations in the gene encoding the Cystic Fibrosis Transmembrane Conductance Regulator (CFTR) protein." (PMID 20379354, 2010). "Cystic fibrosis is a genetic disorder characterized by severe lung dysfunction due to an alteration in an ion transport protein, CF transmembrane conductance regulator (CFTR)." (PMID 20335977, 2010). "Cystic fibrosis is an autosomal recessive disorder caused by defects in the cystic fibrosis transmembrane conductance regulator protein (CFTR), a chloride channel found in the epithelial tissues in the lungs, sinuses, pancreas, skin, and gastrointestinal tract." (PMID 21209785, 2010). "The co-translational rescue of ΔF508 NBD1 misfolding in CFTR by I539T advocates this domain as the most important drug target for cystic fibrosis." (PMID 21152102, 2010). "Cystic fibrosis is the most common life shortening genetic disorder in Caucasians, and occurs in 1 in 3200 Caucasians in the U.S. Since the identification of the CF gene in 1989, over 1500 mutations in the Cystic Fibrosis Transmembrane Conductance Regulator (CFTR) have been associated with CF." (PMID 19169360, 2009). "These nanoparticles have been used in a phase I/II clinical trials to deliver the cystic fibrosis transmembrane regulator (CFTR) gene to cystic fibrosis patients and are also being developed for treatment of genetic brain diseases." (PMID 19823583, 2009). "Delivering CFTR to ciliated cells of cystic fibrosis patients fully restores ion and fluid transport to the lumenal surface of airway epithelium and returns mucus transport rates to those of non-CF airways." (PMID 19621064, 2009). "Cystic fibrosis is an autosomal recessive disorder caused by mutations in the gene encoding the CF transmembrane conductance regulator (CFTR), a cAMP dependent and ATP-gated chloride channel that regulates epithelial surface fluid secretion in respiratory and gastrointestinal tracts." (PMID 19247502, 2009).
cystic fibrosis (continued). "Cystic fibrosis is the most common recessive lethal genetic disorder in Caucasian populations and results from a defect in the CFTR gene." (PMID 19621064, 2009). "Dysfunction of CFTR in cystic fibrosis airway epithelium perturbs the normal regulation of ion transport, leading to a reduced volume of airway surface liquid (ASL), mucus dehydration, decreased mucus transport, and mucus plugging of the airways." (PMID 19621064, 2009). "In the airways, pleiotropic consequences accompanied the production of F508del-CFTR protein generating vicious cycle of airway obstruction, infection, and inflammation at the origin of most of the morbidity and mortality in cystic fibrosis." (PMID 18973672, 2008). "Deletion of a single residue, phenylalanine at position 508, in the first nucleotide binding domain (NBD1) of the Cystic Fibrosis Transmembrane Conductance Regulator (CFTR) is present in approximately 90% of cystic fibrosis patients." (PMID 18463704, 2008). "We propose that Ca2+ homeostasis in cystic fibrosis airway epithelial cells is disturbed and related to the retention in the ER of F508del-CFTR proteins." (PMID 18973672, 2008). "Cystic fibrosis, one of the most common genetic diseases, is characterized by a wide array of recessive mutations in CFTR (cystic fibrosis transmembrane conductance regulator), a Cl- ion channel protein." (PMID 19007437, 2008). "Cystic Fibrosis is an inherited pleiotropic disease that results from abnormalities in the gene that codes for the chloride channel, Cystic Fibrosis Transmembrane Conductance Regulator (CFTR)." (PMID 18628981, 2008). "Altogether, these results suggest reversal of the IP3R dysfunction in F508del-CFTR epithelial cells by a pharmacological correction of the abnormal trafficking of F508del-CFTR in cystic fibrosis cells." (PMID 18973672, 2008). "The cystic fibrosis transmembrane conductance regulator (CFTR) is the channel that is defective in the disease cystic fibrosis." (PMID 17883837, 2007). "CFTR is expressed in organ systems affected by cystic fibrosis, e.g. airways epithelia, the exocrine pancreas, the small intestine, the biliary tract and the male reproductive tract." (PMID 17883837, 2007). "Screening for large genomic rearrangements in the CFTR gene is beneficial not only in classical cystic fibrosis but also in CBAVD, especially for those males who are carriers of a CFTR mild mutation." (PMID 17448246, 2007). "Mouse models of cystic fibrosis, containing disruptions of the CFTR gene, show epithelial bioelectric lesions similar to that observed in CF patients." (PMID 16571124, 2006). "In isolated congenital CFTR dysfunction (cystic fibrosis) an increase in sodium transport by an increase in apical ENaC and basolateral Na/K ATPase activity in the airways can compensate for a reduction in alveolar chloride and sodium transport." (PMID 16571116, 2006). "Since obstructive airway disease in Cystic Fibrosis arises in the small airways and CF is known to be due to mutations in the CFTR gene that expresses a Cl- channel, we asked if this conductance could be due to CFTR." (PMID 15655076, 2005). "For example, recent data suggests that the most common genetic disease in Caucasians, cystic fibrosis, involves mutations in the ABC-cassette transporter protein, CFTR, that confer resistance to infection by Salmonella typhi." (PMID 15522117, 2004). "Moreover, the cell-permeable nanobody enhances the efficacy of approved CFTR modulator drug combination in primary airway epithelial cultures from patients with cystic fibrosis." (PMID 41998105, 2026). "Current evidence linking CFTR dysregulation to respiratory diseases, such as cystic fibrosis, chronic obstructive pulmonary disease (COPD), asthma, and HIV-associated airway disease, as well as cardiovascular, renal, neurological diseases, and cancer, is comprehensively discussed." (PMID 42274626, 2026).
cystic fibrosis (continued). "CFTR potentiators, a clinically validated drug class for cystic fibrosis, offer a compelling model for exploring membrane-targeted design principles, as their efficacy depends on sustained intramembrane binding to prolong channel opening and chloride conductance." (PMID 42046515, 2026). "In vitro validation of a CRISPR/Cas9-mediated gene correction strategy for cystic fibrosis has been performed in pig cells, which demonstrated the precise integration and persistent functional expression of the human cystic fibrosis transmembrane conductance regulator (CFTR) gene." (PMID 41362674, 2026). "Due to the introduction of CFTR modulators and yet unknown long-term effects, it is possible that new criteria need to be established for referral in the cystic fibrosis patient population in the near future." (PMID 40276963, 2025). "None of the samples tested revealed a genetic diagnosis of cystic fibrosis, that is, no participant had homozygous or compound heterozygous mutations in CFTR in variants known to be associated with a cystic fibrosis phenotype." (PMID 40333927, 2025). "Finally, there are people with cystic fibrosis who have discontinued elexacaftor–tezacaftor–ivacaftor due to a variety of reasons and have an unmet need for another CFTR modulator treatment option." (PMID 39756424, 2025). "Patients with cystic fibrosis have dysfunctional cystic fibrosis transmembrane conductance regulator (CFTR), and this predisposes them to nontuberculous mycobacteria (NTM), including Mycobacterium abscessus (MAB), infection." (PMID 40372084, 2025). "Interestingly, Cystic Fibrosis Transmembrane Conductance Regulator Modulator Therapy (CFTR) has recently been introduced for the treatment of CF in children." (PMID 41464737, 2025). "Variants in CFTR are known to cause cystic fibrosis, and its role in neurodevelopment is not well established." (PMID 41442065, 2025). "Unlike cystic fibrosis, in which 90% patients carry one or two copies of a highly prevalent trafficking mutation ΔF508 in CFTR, there is no single highly prevalent mutation in the KATP channel that underlies channel trafficking defects." (PMID 40135739, 2025). "For instance, the cystic fibrosis drug Trikafta, which combines two correctors to promote proper folding and trafficking of the F508del CFTR mutant and a potentiator to enhance channel activity, has significantly improved outcomes in patients with folding-defective variants." (PMID 40870031, 2025). "Recent evidence indicates that CFTR modulators—particularly highly effective combinations such as elexacaftor/tezacaftor/ivacaftor—produce measurable reductions in airway inflammation in people with cystic fibrosis." (PMID 41154689, 2025). "Consequently, the autophagy substrate SQSTM1/p62 accumulates, trapping misfolded F508del-CFTR and key anti-inflammatory proteins such as PPARγ and IκBα in intracellular aggresomes, perpetuating a pro-inflammatory environment in cystic fibrosis airways." (PMID 40430792, 2025). "Ivacaftor is a CFTR potentiator commercialized for cystic fibrosis treatment, which, based on previous findings, could have a therapeutical effect on CeD." (PMID 41010485, 2025). "ENaC is subjected to a complex array of post-translational regulatory processes – including protease activation and CFTR inhibition, which has been studied in relation to cystic fibrosis – but there is little known of ENaC regulation in relation to ciliary motility in PCD." (PMID 41064994, 2025). "It is very important to be able to qualify patients who do not meet diagnostic criteria for cystic fibrosis, while CFTR channel dysfunction has been proven." (PMID 40943780, 2025). "Unraveling its regulation could clarify the clinical heterogeneity observed in cystic fibrosis and CFTR-related disorders." (PMID 40332394, 2025).